CCDC82 (coiled-coil domain containing 82)
Synonyms: FLJ23518; HSPC048
Tractability: PROTAC: ubiquitination databases record sites on it.
Gene: Protein-coding gene on chromosome 11 (96,349,241 to 96,389,956, reverse strand). Ensembl gene ENSG00000149231.
Subcellular location (Human Protein Atlas): Nucleoplasm; Cytosol; Nuclear bodies
Gene Ontology:
Cellular component: nucleus
Genetic constraint (gnomAD): Loss-of-function variants: 28 observed, 36.21 expected, observed/expected ratio (o/e) 0.77, 90% interval 0.57 to 1.06. The upper end of that interval is the gene's LOEUF score, 1.06, which puts it in group 4 of 6, group 1 being the genes least tolerant of losing a copy. Missense variants: 384 observed, 417.92 expected, observed/expected ratio (o/e) 0.92, 90% interval 0.84 to 1. Synonymous variants: 134 observed, 133.35 expected, observed/expected ratio (o/e) 1, 90% interval 0.87 to 1.16.
Homologues: Orthologues: chimpanzee CCDC82 (99% identical), macaque CCDC82 (86% identical), dog CCDC82 (81% identical), pig CCDC82 (77% identical), guinea pig CCDC82 (73% identical), rabbit CCDC82 (70% identical), mouse Ccdc82 (69% identical), rat Ccdc82 (67% identical), tropical clawed frog ccdc82 (35% identical), zebrafish ccdc82 (29% identical), Drosophila melanogaster CG17233 (18% identical).
Diseases named in the same sentence as CCDC82 in open-access papers:
CCDC82 is named in the same sentence as 5 diseases in open-access papers, as found by Europe PMC text mining. Sharing a sentence is not in itself a finding about the gene and the disease. The quoted sentences say what the papers report.
breast carcinoma (2 papers, 2019 to 2020). "Moreover, rs3842515, which showed the strongest association with sensitivity to ACNU in breast cancer xenograft, displayed a cis-regulatory effect on CCDC82 expression in several tissues, including esophagus, thyroid, skin, and nerve (Pmin = 2.3 × 10−13)." (PMID 32986753, 2020).
Huntington disease (1 paper, 2025). Huntington disease (HD) is a rare neurodegenerative disorder of the central nervous system characterized by unwanted choreatic movements, behavioral and psychiatric disturbances and dementia. "For example, our reassessment of modifiers of mHTT toxicity in zQ175 mice showed an overlap with Huntington’s disease modifier genes CCDC82 and TCERG1." (PMID 39801710, 2025).
intellectual disability syndrome (1 paper, 2024). "CCDC82 was reported previously to cause an intellectual disability syndrome." (PMID 37012327, 2024).
Spastic paraplegia (1 paper, 2024). Complete loss of the ability to move the lower limbs accompanied by spasticity of the lower limbs. "We expanded the CCDC82-linked phenotype to include spastic paraplegia." (PMID 37012327, 2024).
CCDC82 also shares sentences with these, for which no sentence is quoted: Intellectual disability (1 paper).